LRG1 (leucine rich alpha-2-glycoprotein 1)
Diseases named in the same sentence as LRG1 in open-access papers (continued):
Sharing a sentence is not in itself a finding about the gene and the disease.
acute appendicitis (continued). "When combined with a clinical suspicion of acute appendicitis, the results suggest that LRG1 levels in serum have a high biomarker potential for confirming the acute appendicitis diagnosis in pediatric patients." (PMID 37048540, 2023). "Our results reinforce several recent publications that indicated a connection between an increased LRG1 level and the established diagnosis of acute appendicitis in the pediatric population." (PMID 37048540, 2023). "In previous research studies, an elevation of LRG1 in the appendix as well as in the serum and urine of children with a confirmed diagnosis of acute appendicitis had been discovered." (PMID 37047015, 2023). "The results demonstrated that LRG1 in saliva allows for an effective distinction to be made between acute appendicitis and the controls (AUC = 0.85; 95% CI 0.76–0.92; p < 0.001)." (PMID 37047015, 2023). "A novel protein biomarker known as leucine-rich alpha-2-glycoprotein 1 (LRG1) has recently been found in the diseased appendices and has been elevated in the serum, urine and saliva of patients with acute appendicitis." (PMID 37048540, 2023). "The results of our study showed that LRG1 in the serum enabled a 100% accurate separation between acute appendicitis and controls at the determined threshold concentration of 69.1 μg/mL." (PMID 37048540, 2023). "Circulating human mRNA and protein levels of LRG1 had good prediction ability for acute appendicitis in adults or children." (PMID 35095520, 2021). "There is a need to confirm the results by other centers and using different ELISA kits before implementing LRG1 as a biomarker for diagnosing appendicitis." (PMID 33692371, 2021). "u-LRG1 levels of pediatric appendicitis patients were significantly elevated in comparison to the control group in this study (0.10–0.35 μg/mL and 0.04 μg/mL respectively, p < 0.001)." (PMID 34064691, 2021). "Increased LRG1 expression was also found in patients undergoing neurodegenerative diseases, acute appendicitis, hydrocephalus, heart failure, autoimmune diseases, and ageing." (PMID 27378305, 2016). "Neither serum not urine LRG1 concentrations were significantly associated with the odds of complicated appendicitis." (PMID 40208339, 2025). "Based on the results from previous studies indicating a positive association between increased LRG1 concentrations and appendicitis, the test was set up in a similar matter and not inversed." (PMID 40208339, 2025). "Our results indicate that urine LRG1 might have the potential to differentiate between uncomplicated and complicated appendicitis in children, but with a lesser accuracy than currently more readily available diagnostic aids such as CRP and AIR score." (PMID 40208339, 2025). "Additionally, LRG1 levels were significantly higher in patients with perforated appendicitis than in those with uncomplicated disease (p = 0.05)." (PMID 41153524, 2025). "The median urine LRG1 concentration in the uncomplicated appendicitis group was 0.10 (IQR 0.02–0.29) μg/mL, which is significantly lower than in the no appendicitis group (0.33 [0.10–0.72] μg/mL) and in the complicated appendicitis group (0.29 [0.12–1.07] μg/mL), p < 0.001." (PMID 40208339, 2025). "Neither serum nor urine LRG 1 were significantly associated with the odds of complicated appendicitis." (PMID 40208339, 2025). "Although LRG1 in saliva showed a good AUC parameter and significantly higher values in patients with acute appendicitis compared to the controls, its usefulness in a patient population who present at the hospital emergency department with abdominal pain is debatable." (PMID 37047015, 2023). "In addition, LRG1 proved to be an excellent serum biomarker with very high sensitivity and specificity in the detection of acute appendicitis in children." (PMID 37189999, 2023). "Salivary LRG1 levels increase with the severity of appendicitis." (PMID 37047015, 2023).
acute appendicitis (continued). "When we compare these results with our previous study on saliva-measured LRG1, in the same cohort of patients, we can clearly see that serum-measured LRG1 has a significantly higher sensitivity for detecting acute appendicitis in the pediatric population than saliva-measured LGR1." (PMID 37048540, 2023). "Serum LRG1 has been shown to be an excellent biomarker for acute appendicitis in children." (PMID 37048540, 2023). "A more recent study showed that non-invasive markers from saliva, such as leucine-rich α-2-glycoprotein 1 (LRG1), may be promising biomarkers for the detection of acute appendicitis in children." (PMID 37189999, 2023). "Consequently, the objective of our study is to analyze the applicability of salivary LRG1 in the diagnosis of acute appendicitis in the pediatric population." (PMID 37047015, 2023). "The results demonstrated a statistically significant increase in LRG1 in the saliva of children with acute appendicitis compared with the control group, allowing for the effective discrimination between acute appendicitis and controls (AUC = 0.85, 95% CI 0.76–0.92, p < 0.001)." (PMID 37238401, 2023). "Recent studies have suggested that leucine-rich α-2-glycoprotein 1 (LRG1) may serve as a biomarker for acute appendicitis in the pediatric population." (PMID 37047015, 2023). "However, there were also studies that showed that plasma levels of LRG1 were ineffective in the diagnosis of acute appendicitis in female patients accompanied by acute abdominal pain." (PMID 35095520, 2021). "The primary study objective is to demonstrate that LRG1 could potentially differentiate AcA from AuA in a prospective cohort study with cases of pediatric acute appendicitis." (PMID 34064691, 2021). "This study demonstrated that patients with appendicitis had significantly elevated s-LRG1 and u-LRG1 concentrations compared to the control group and had a significant difference of s-LRG1 concentrations in AcA and AuA, indicating that s-LRG1 correlates with the severity of appendicitis." (PMID 34064691, 2021). "Some studies found that circulating LRG1 mRNA and plasma LRG1 protein levels might together be helpful for diagnosing simple and complicated acute appendicitis in patients with acute abdominal pain." (PMID 33132754, 2020). "It is suggested that LRG1 may be a useful marker of pediatric appendicitis as it was elevated in urine and plasma of children with acute appendicitis and enriched in diseased appendices." (PMID 27378305, 2016). "The diagnostic utility of urine LRG1 should be evaluated in a different setting, since it probably could come to best use in patients with a low pretest probability for appendicitis, in order to rule out the diagnosis and send the patient home without any blood sampling." (PMID 40208339, 2025). "During recent years, leucine-rich alpha-2 glycoprotein 1 (LRG1) has emerged as a potentially promising predictor of both pediatric appendicitis and complicated appendicitis." (PMID 40208339, 2025). "Leucine-rich Alpha-2 Glycoprotein (LRG1) is a novel biomarker and is hypothesized to not only have a particularly vital and rapid diagnostic precision ratio, but also can determine specificity in acute appendicitis development with drug-independent serum-values." (PMID 34064691, 2021). "Several studies have shown that serum LRG1 levels rise significantly in patients with acute appendicitis compared to healthy controls and those with nonspecific abdominal pain." (PMID 41153524, 2025). "Still, their results indicate a good diagnostic performance of serum LRG1, especially one in which there was no overlap between serum LRG1 concentrations in the patients with and without appendicitis, generating an astonishing ROC AUC of 1.0." (PMID 40208339, 2025). "The objective of this study is to compare the plasma levels of LRG1 in an adult population with and without the diagnosis of appendicitis, using a commercial ELISA kit." (PMID 33692371, 2021).
acute appendicitis (continued). "In conclusion, our findings show that median plasma levels of leucine-rich alpha-2-glycoprotein 1 are not different between cases with and without acute appendicitis." (PMID 33692371, 2021). "It is therefore possible that urine LRG1 could be best used to rule out appendicitis in patients with a low pretest probability, and evaluation of the biomarker in this setting, for example at a primary care facility, would be of great interest." (PMID 40208339, 2025). "According to their study, LRG1 could serve as a sensitive but non-specific indicator of acute appendicitis." (PMID 37047015, 2023).
lung carcinoma (21 papers, 2012 to 2025). "Supporting the observation as a generalizable notion, with respect to a single protein, LRG1, we have recently described that epitope-specific autoantibody levels are differentially associated with lung cancer." (PMID 37211046, 2023). "Clinical analysis of urine samples showed stronger anti-LRG1-AuR signals in lung cancer patients than in healthy controls, suggesting the approach’s potential for identifying early-stage lung cancer patients." (PMID 40277513, 2025). "Using anti-LRG1 antibody-conjugated AuR probes, the differential expression of LRG1 (leucine-rich alpha-2-glycoprotein 1) in urinary EXOs of lung cancer patients and healthy individuals was analyzed." (PMID 38816782, 2024). "In Lewis lung cancer cells, the overexpression of LRG1 has been found to enhance the SMAD2 signaling pathway, which is also activated by TGF-β1." (PMID 37569820, 2023). "A proteomic study of lung cancer patients revealed high expression of LRG1 in urinary exosomes and lung tissue, suggesting that this protein can be a potential biomarker." (PMID 34503141, 2021). "Based on previous research, several biomarkers have been described in exosomes of lung cancer (compared to normal tissue samples), including several miRNAs and EpCAM from plasma exosomes and LRG1 from urine exosomes." (PMID 30733650, 2019). "It was found that other tumor-specific proteins included plasma exosomal surface EGFR or leucine-rich alpha-2-glycoprotein (LRG1) in urinary exosomes, which were identified in lung cancer patients." (PMID 29282096, 2017). "RT-PCR validation of expression of introns of DLK1 and LRG1, lung cancer genes verified the results of the bioinformatic analyses." (PMID 26805894, 2016). "Increased LRG1 levels have been observed in serum or plasma of patients with various types of cancers including lung cancer." (PMID 27378305, 2016). "Using RT-PCRs, we validated the expression of introns of two oncogenes, DLK1 and LRG1, known to be key players in lung cancer progression, and demonstrate changed intronic expression with supplement treatment in cancer cells." (PMID 26805894, 2016). "We revealed that A1BG and LRG1 were overexpressed in both the blood level and tumor sections, which can be referred to separate lung cancer patients from healthy cases." (PMID 23284758, 2012). "Additionally, exosomal leucine-rich α-2-glycoprotein (LRG1) has been reported as a potential biomarker for lung cancer detection, capable of effectively distinguishing early-stage lung cancer from normal controls using urine samples." (PMID 41573685, 2025). "LRG1 is significantly expressed in exosomes from the urine of lung cancer patients." (PMID 40277513, 2025). "Furthermore, we experimentally validate the expression of introns of two oncogenes, DLK1 and LRG1, which are major players in lung cancer progression." (PMID 26805894, 2016). "Interestingly, A1BG and LRG1 were reported to be secreted by the A549 cell line and were found to be elevated in the serum of lung cancer patients." (PMID 26133466, 2015). "However, the specificity for lung cancer is expected to be low as other cancers also express LRG1." (PMID 34503141, 2021). "Exosomal proteomes have identified several exosomal proteins, including CD317, EGFR, leucine-rich a2-glycoprotein (LRG1), alpha-2-HS-glycoprotein (AHSG), and extracellular matrix protein 1 (ECM1), that hold the potential to serve as indicators for lung cancer early detection." (PMID 40559625, 2025).
ovarian carcinoma (21 papers, 2010 to 2025). A malignant neoplasm originating from the surface ovarian epithelium. "This approach successfully identified cysteine-containing peptides from LRG-1 (Leucine-Rich Alpha-2-Glycoprotein 1), a protein biomarker specific to ovarian cancer that is present in the urine of affected women." (PMID 40863000, 2025). "LRG1 is a secretory glycoprotein which is overexpressed in multiple cancers such as pancreatic, bladder and ovarian cancers." (PMID 34930899, 2021). "Some studies are in accordance with the present study that miR‐497 expression was reduced in breast cancer and in multiple myeloma samples and cell lines 19, 20 while LRG1 expression was up‐regulated in hepatocellular carcinoma and in ovarian cancer." (PMID 32975015, 2020). "Leucine-rich alpha-2-glycoprotein (LRG1) was found to be differentially expressed in sera from patients with Epithelial Ovarian Cancer (EOC)." (PMID 25799488, 2015). "In previous work, we found the abnormal expression of LRG1 in ovarian cancer, including in early stage cases." (PMID 25799488, 2015). "Herein, we further validated our findings using two independent blinded sample sets to evaluate the performance of LRG1 or in conjunction with CA125 in detecting ovarian cancer." (PMID 25799488, 2015). "The expression of LRG1 in ovarian cancer tissues and cell lines was examined by gene microarray, reverse-transcriptase polymerase chain reaction (RT-PCR), Western blot, immunocytochemistry and mass spectrometry." (PMID 20831812, 2010). "Four proteins were shown to have increased levels in ovarian cancer serum by both proteomic methods: haptoglobin, alpha-1 antichymotrypsin, serum amyloid P-component, and LRG1." (PMID 20546617, 2010). "Because surface epithelial cells comprise only a minor fraction of the normal ovary, we also examined the expression of LRG1 protein in cell lines derived from ovarian cancer cells and normal ovarian surface epithelia." (PMID 20831812, 2010). "Although identified based on a single peptide, the average iTRAQ® protein ratio for LRG1 was made from three (replicate) peptide spectra, and the ratio was ~2.9-fold higher in ovarian cancer relative to control sera." (PMID 20546617, 2010). "In Western blot analysis of cell lines, the ~47 and ~51 kD forms of LRG1 protein were present in both ovarian cancer and NOSE cell lines; the predominant form detected in all cases was 47 kD." (PMID 20831812, 2010). "One such differentially expressed protein, leucine-rich α-2-glycoprotein-1 (LRG1), is ~3-fold more abundant in ovarian cancer serum compared to non-cancer control serum, and represents a potential serum biomarker for ovarian cancer." (PMID 20831812, 2010). "The protein LRG1 was determined to have robustly increased levels of expression in ovarian cancer sera by iTRAQ®." (PMID 20546617, 2010). "LRG1 expression in ovarian cancer sera was validated by Western blot in the immunodepleted serum pools, and by ELISA in individual, undepleted serum samples (data not shown)." (PMID 20546617, 2010). "LRG1 protein was detected in ovarian cancer tissue samples and cell lines by immunocytochemistry and Western blotting." (PMID 20831812, 2010). "The mean LRG1 concentration for ovarian cancer patient sera was 89.33 ± 77.97 μg/ml compared to 42.99 ± 9.88 μg/ml for non-cancer sera." (PMID 20831812, 2010). "We previously demonstrated the upregulation of leucine-rich alpha-2-glycoprotein-1 (LRG1) in the sera of ovarian cancer patients compared to healthy women using quantitative mass spectrometry." (PMID 20831812, 2010). "All seven ovarian cancer specimens demonstrated higher levels of LRG1 protein than the five normal ovaries." (PMID 20831812, 2010). "LRG1 mRNA levels were higher in ovarian cancer tissues and cell lines compared to their normal counterparts when analyzed by gene microarray and RT-PCR." (PMID 20831812, 2010).
ovarian carcinoma (continued). "LRG1 was quantified by ELISA in serum from two relatively large cohorts of women with ovarian cancer and benign gynecological disease." (PMID 20831812, 2010). "To control for the possible influence of stromal, endothelial, and blood cells present in tissue samples, we examined LRG1 mRNA expression levels in ovarian cancer and NOSE cell lines by RT-PCR." (PMID 20831812, 2010). "Ovarian cancer patients had a statistically significant ~2-fold increase in serum LRG1 compared to healthy controls (age adjusted, p = 0.0008)." (PMID 20831812, 2010). "We recently identified leucine-rich alpha-2-glycoprotein-1 (LRG1) as one of several proteins overexpressed in the serum of patients with ovarian cancer." (PMID 20831812, 2010). "The increased serum LRG1 levels in ovarian cancer patients that we had observed by Western blot in pooled samples, were also evident by ELISA in individual samples." (PMID 20831812, 2010). "Mean serum LRG1 was higher in 58 ovarian cancer patients than in 56 healthy women (89.33 ± 77.90 vs. 42.99 ± 9.88 ug/ml; p = 0.0008) and was highest among stage III/IV patients." (PMID 20831812, 2010). "Serum LRG1 was significantly elevated in women with ovarian cancer compared to healthy women and women with benign gynecological disease, and was only moderately correlated with CA125." (PMID 20831812, 2010). "LRG1 protein was also detected in the conditioned media of ovarian cancer cell culture by ELISA, Western blotting, and mass spectrometry." (PMID 20831812, 2010). "Given that murine LRG1 has been shown to bind to several extracellular matrix proteins, and also TGFβ, a possible role for LRG1 in ovarian cancer progression is intriguing." (PMID 20831812, 2010). "We have previously shown by DIGE analysis of immunodepleted sera that levels of AACT and LRG1 expression are increased in ovarian cancer sera, and validated this by Western blot." (PMID 20546617, 2010). "LRG1 could be a useful biomarker alone or in combination with CA125 for the diagnosis of ovarian cancer." (PMID 25799488, 2015). "We have also shown that ovarian cancer cells may directly contribute to the elevated levels of LRG1 observed in patients' sera." (PMID 20831812, 2010). "LRG1 also localized to the plasma membrane in most of the ovarian cancer cell lines." (PMID 20831812, 2010). "To determine whether ovarian cells secrete LRG1 and thus may directly contribute to the elevated levels of LRG1 protein observed in the ovarian cancer patients' sera, we analyzed serum-free conditioned media from NIH:OVCAR5 cells using mass spectrometry." (PMID 20831812, 2010). "Taken together, these results demonstrate that, in addition to being synthesized in the liver, ovarian cancer cells synthesize and secrete LRG1, and may therefore contribute to the elevated LRG1 levels observed in the sera of the ovarian cancer patients." (PMID 20831812, 2010). "We have demonstrated the potential for using LRG1 as a serum biomarker for ovarian cancer." (PMID 20831812, 2010). "We have previously shown an increase in several LRG1 isoforms in ovarian cancer serum by DIGE." (PMID 20546617, 2010). "The N-glycosylation of LRG1 produced by the ovarian cancer cells is consistent with its secretion." (PMID 20831812, 2010). "LRG1 peptides have also been identified in ascites fluid and cells from ovarian cancer patients." (PMID 20831812, 2010). "Six of the eight ovarian cancers expressed higher levels of LRG1 mRNA than normal ovaries." (PMID 20831812, 2010). "To determine whether the ovarian cancer cells may serve as a potential source of the increased serum LRG1 levels in ovarian cancer patients, we quantified LRG1 mRNA expression in ovarian tumors compared to normal ovaries by gene microarray analysis." (PMID 20831812, 2010). "Similar to our study, they found LRG1 levels were increased in ovarian cancer serum." (PMID 20546617, 2010).